RET (ret proto-oncogene)
Diseases named in the same sentence as RET in open-access papers (continued):
Sharing a sentence is not in itself a finding about the gene and the disease.
tumor (continued). "RET/PTC3 was the most common type in tumours with short latency (4–8 years after the exposure), whereas tumours developed after longer period of time had RET/PTC1 predominantly." (PMID 26584635, 2015). "Seven tumor samples were classified as positive for RET rearrangements (vandetanib treatment, n = 3; comparator treatment, n = 4)." (PMID 25881079, 2015). "Her clinical and CEA tumor marker responses suggested regorafenib has single agent activity in RET fusion positive CRC." (PMID 26078337, 2015). "RET protein appears to be largely cytoplasmic; however, considerable inter-patient variation and heterogeneity among tumor cells within individual tumors is observed." (PMID 25881079, 2015). "Somatic mutations in inherited PCC/PGL genes can be detected in ~25–30% of the sporadic tumours (mainly involving RET, VHL, NF1, MAX, and HIF2A genes)." (PMID 25883647, 2015). "In specific cases, RET screening and genotype and phenotype correlation permits prophylactic surgery for an aggressive tumor." (PMID 26347711, 2015). "Because of the strong involvement of RET/PTC3 fusion oncogene in tumour development, gene inhibition therapy specifically targeting RET/PTC3 would be an alternative and personalised therapy for PTC harbouring this junction oncogene." (PMID 24759995, 2014). "Since RET/PTC3 was found to be involved in tumour transformation, it can be considered as a potential target for a therapeutic approach." (PMID 24759995, 2014). "Since, RET/PTC3 is only present in the tumour cells, thus represents an interesting target for specific therapy by small interfering RNA (siRNA)." (PMID 24759995, 2014). "In order to test the ability of transformed NIH/3T3 with RET/PTC3 to give tumours, NIH/3T3 or RP3 cells were injected sub-cutaneously to nude mice at 0.5, 1.0 or 2.0×106 cells/mouse." (PMID 24759995, 2014). "We found variants in the five genes APC, BRCA1, RET, RNASEL, and STK11 that were linked to autosomal dominant forms of cancer or neoplasm as well as four complex risk variants in ELAC2, MSR1, AIP, and SDHB." (PMID 25333069, 2014). "Our data indicate that MassARRAY-based multiplex genetic testing both for somatic mutations and for ALK, ROS1, and RET fusion genes performed well with nucleic acid (DNA and RNA) extracted from FFPE tumor specimens obtained from patients with advanced NSCLC." (PMID 24810493, 2014). "Using vandetanib, we show that RET inhibition strongly impairs tumor growth in vivo in both MYCN/KI AlkR1279Q and MYCN/KI AlkF1178L mice." (PMID 24811913, 2014). "Taken together, these results showed that we successfully designed an efficient and specific siRNA capable of targeting the RET/PTC3 sequence which is only expressed in tumour cells." (PMID 24759995, 2014). "Tumours were collected at day-8 and RET/PTC3 gene expression was verified by RT-PCR followed by agarose gel electrophoresis revealing persistent RET/PTC3 junction oncogene expression in all collected tumours." (PMID 24759995, 2014). "Ten variants were identified from eight genes in both the tumor and normal groups (APC, EGFR, FGFR3, KDR, MET, PDGFRA, RET and SMO)." (PMID 25404506, 2014). "A recent study investigated the effects of motesanib on wild-type and mutant RET activity in vitro and on tumor xenograft growth in a mouse model of MTC." (PMID 23509459, 2013). "It was proposed that RAS/BRAF and/or PI3K/AKT pathways are required for cellular transformation and that the additional proinflammatory pathways of RET/PTCs shape the features of the growing tumor." (PMID 24868250, 2013). "RET/PTC induces these significant phenotypic changes oriented toward neoplastic transformation affecting the tumor microenvironment." (PMID 24868250, 2013). "We identified mild to moderate levels of RET expression in all of the 18 human ACC tumor specimens assessed." (PMID 22768171, 2012). "While message for RET was identified in all tumor samples, this RTK was found to be phosphorylated in only 54% of AGASACA and 20% of TC samples." (PMID 22630170, 2012).
tumor (continued). "Thyroglobulin (TG) and thyroid peroxidase (TPO) expression was found to be significantly decreased in tumors, and the lowest level of TPO expression occurred in a tumor harboring both the p.A67GTTF-2 variant and a RET/PTC3 rearrangement." (PMID 22481925, 2012). "In the current study, DNA from a primary tumor and a lymph node metastasis of a persistent SMTC patient, harboring the M918T RET mutation, was subjected to CGH analysis to evaluate additional genetic changes." (PMID 22676344, 2012). "Although HB-19 treatment failed to prevent the development of spontaneous melanoma in the RET mice, it delayed significantly the onset and frequency of cutaneous tumors, and reduced visceral metastasis and tumor vascularization." (PMID 20573279, 2010). "In a more relevant tumor model, now we provide evidence that HB-19 can also interfere with the spontaneous development of cancer in RET mice." (PMID 20573279, 2010). "It displays antitumor activity by directly inhibiting tumor cell proliferation and survival via EGFR and RET inhibition, as well as tumor angiogenesis via VEGFR inhibition." (PMID 19390592, 2009). "We analysed RET exons 5, 8, 10–16 in fifty-one sporadic MTC, and found somatic mutations in thirty-three (64.7%) tumours." (PMID 19401695, 2009). "We know much about the pathology of RET/PTC human tumours but much less about their biological evolution." (PMID 18985036, 2008). "During tumour development a large heterogeneity occurred in the Tg-RET/PTC3 model within a same tumour or within a same thyroid lobe." (PMID 18985036, 2008). "After the progression, the molecular testing revealed CCDC6-RET fusion in a liver metastasis, two novel RET fusions (IL6ST-RET and SLC41A3-RET), and an ALK fusion with a mutation allele frequency of 0.19% in circulating tumor DNA (ctDNA), including the known EGFR 19del." (PMID 41907614, 2026). "Regulatory approvals of therapies targeting tumors harboring genomic alterations such as NTRK and RET fusions, BRAF V600E mutation, and those with deficient mismatch repair (dMMR) and a high tumor mutational burden (TMB-H) have demonstrated clinical activity across multiple cancer types." (PMID 42192928, 2026). "The KIF5B [Exon 1-15] | RET [Exon 12- 19] fusion was selected from a patient-derived xenograft (PDX) model based on its established role as an actionable cancer driver in an independent tumor with the same junction." (PMID 41246330, 2025). "If confirmed by further studies, this may indicate a high degree of homogeneity with respect to the RET protooncogene within the tumour." (PMID 40729029, 2025). "RET p.G691S is widely reported in the literature as a non-synonymous (germline) polymorphism in normal populations, but even more frequent in some tumor series." (PMID 41517303, 2025). "However, this trial was not included in the current meta-analysis, as it only enrolled two ATC patients among 166 individuals with RET-driven tumours." (PMID 40075624, 2025). "However, it can prove beneficial in specific situations, particularly as targeted therapy for RET gene fusion-positive tumours." (PMID 40141188, 2025). "The combination of high-throughput assays aimed at identifying the common mutations such as BRAF, RET, and RAS and at evaluating ctNAs can provide important information about the mutational spectrum of the tumor and guide the selection of appropriate targeted therapy." (PMID 40095491, 2025). "The high lesion index (InL) observed in the RET 40 μM, B[a]P 10 μM and DMBA 10 μM groups suggest that RET may contribute to skin carcinogenesis." (PMID 40211435, 2025). "In this patient, the homogeneous detection of RET across different tumour sites supports this view." (PMID 40729029, 2025). "In contrast, subtype C2 predominantly features mutations in genes involved in kinase signaling pathways, including NF1 and RET, which imply active signaling networks that could influence tumor growth and response to therapies." (PMID 41400463, 2025).
tumor (continued). "Whether tumor recurrence is related to mutations in MKNK1, POLE, RET, RTEL1, RUNX1T1, TAP1 still requires further research for validation." (PMID 40901169, 2025). "The mechanisms underlying this resistance are heterogeneous and can be divided into two categories: target-dependent alterations, which directly involve the RET gene, and target-independent alterations, which include activation of alternative oncogenic pathways or phenotypic changes in the tumor." (PMID 41465145, 2025). "In this family, as in the present case, coexistence of MEN1 and RET mutations did not alter tumor onset, behavior or typical phenotype compared to patients with isolated mutations." (PMID 40476723, 2025). "BRAF V600E was found in RET-negative tumours, with novel mutations (G469A and T599dup), suggesting BRAF as a scarce driver of MTC carcinogenesis." (PMID 40332222, 2025). "While RET gene fusions are not commonly associated with HGSOC, the National Comprehensive Cancer Network (NCCN) guidelines recommend testing for RET gene fusions and administering therapy with selpercatinib in patients whose tumours are positive for these fusions." (PMID 40141188, 2025). "Notably, studies have shown that RET inhibitors can enhance the efficacy of immunotherapy by regulating the tumor microenvironment." (PMID 41278287, 2025). "In summary, RET/PTC rearrangements are a crucial molecular event in thyroid cancer, especially in PTC, and are strongly associated with aggressive disease, frequent metastasis, and rapid tumor growth." (PMID 40507982, 2025). "Testing for mismatch repair (MMR)/microsatellite instability (MSI), tumor mutational burden (TMB), NeuroTrophin Receptor Kinase (NTRK), and proto-oncogene tyrosine-protein kinase receptor (RET) can assist in identifying potential therapeutic targets for patients." (PMID 40375998, 2025). "Several biomarkers not included in the survey are also important to test for in mBC, including RET fusions, NTRK fusions in the case of secretory carcinomas, as well as high tumor mutational burden (TMB) and high microsatellite instability (MSI) if the use of pembrolizumab is being considered." (PMID 40344957, 2025). "In summary, this study suggests that RET, an environmental contaminant, may possess both tumour‐initiating and tumour‐promoting properties, as demonstrated by computational modelling and in vivo experimentation." (PMID 40211435, 2025). "Additionally, tumor biopsies from RET-rearranged NSCLC patients who exhibited cancer progression on RET inhibitor therapy were analyzed." (PMID 40405293, 2025). "In summary of the analysis of the primary tumour vs. LNM, the evaluation of the mutation classified as reliably pathogenic (RET gene (chr10:43609933, c.1886_1891delTGTGCG; RB1 gene, chr13:49033890, c.2039T>C) shows a match between primary tumour tissue and LNM." (PMID 40729029, 2025). "RET/PTC3 mice showed 28% tumour rate; E7 phenotype dominant in co-expression." (PMID 41479925, 2025). "The development and progression of these tumours are not always predictable even within families with the same RET pathogenic variant, demonstrating a need for better understanding of the underlying molecular mechanisms." (PMID 40316714, 2025). "Moreover, ICC exhibits unique mutation enrichments, such as IDH1/2 mutation, NTRK gene fusions, FGFR2 fusions/rearrangements, and RET fusions, particularly IDH1 mutations, which have higher mutation frequencies than other tumor types." (PMID 41236411, 2025). "Notably, we observed a significant increase in EGFR expression in tumor biopsies from NSCLC patients treated with RET inhibitors who experienced disease progression, further validating the clinical relevance of our findings." (PMID 40405293, 2025).
tumor (continued). "Clinical evaluation of these agents has been conducted through basket trials, which enroll patients based on the presence of defined genomic alterations (e.g., RET rearrangements or mutations) rather than tumor histology." (PMID 41465145, 2025). "While selpercatinib has demonstrated efficacy in treating RET fusion-positive tumours, vigilant monitoring and management of adverse events, particularly those related to laboratory abnormalities and serious reactions, are pivotal components of patient care during selpercatinib therapy." (PMID 40141188, 2025). "Additionally, rearranged during transfection (RET) during protein expression was found to lead to tumor enlargement, resulting in a later patient stage, while colchicine selectively binds to RETg, perhaps exerting an antitumor effect." (PMID 37646984, 2024). "Hence, if the signaling by RET within the tumor cells is impeded, the tumors will fail to facilitate the infiltration of MDSCs, resulting in immune activation and subsequently eliciting an immunotherapeutic response." (PMID 38473324, 2024). "Large tumor sizes greater than 4 cm, high levels of Ctn, high CEA, high CA19.9, high-grade tumors, tumors with areas of desmoplastic reaction or lympho-vascular invasion, and/or RET proto-oncogene mutations increase the likelihood of distant metastasis." (PMID 39456563, 2024). "The categorization of hereditary MTC into moderate, high, or highest risk based on the codon of the RET proto-oncogene mutated is relevant when the tumor is early, but not when it is advanced, as the outcome is similar for advanced stages of the disease." (PMID 39456563, 2024). "One of the key strengths of this study is that, despite the rarity of RET alterations making it challenging to study patients with such alterations in real-world databases, this study was able to present findings from two data sources across tumor types." (PMID 39594790, 2024). "RET fusions were significantly more frequent in women and patients with normal serum tumor markers." (PMID 39364008, 2024). "The combination of variants in the RET (rs587778656) and POLE (rs1064796427) genes could be involved in tumor development." (PMID 39273494, 2024). "Mechanistically, these inhibitors increased mitochondrial membrane potential (Δψm) in the RET tumor cells, subsequently facilitating tumor cell uptake and retention of Δψm-sensitive triphenyl phosphonium (TPP)-conjugated carboxy-proxyl (MitoCP) and ubiquinone (MitoQ)." (PMID 38378752, 2024). "In addition, CCDC6 has subsequently been described as being involved in other rearrangements, in addition to RET, in different neoplasias." (PMID 39684377, 2024). "Indeed, RET seems to be involved in tumor progression, resistance to therapies, and cellular proliferation." (PMID 39211557, 2024). "The authors surmised that it is possible that RET RNA splicing might be dysregulated in tumor cells." (PMID 38566816, 2024). "We thus reasoned that the property of RET inhibition to increase Δψm could be exploited to drive mitochondrial enrichment of MitoQ more effectively in tumor cells beyond the threshold to disrupt a bioenergetics balance." (PMID 38378752, 2024). "Additionally, mutations in tyrosine kinase receptors, such as RET mutations in MTC, contribute to tumor proliferation and survival." (PMID 39767725, 2024). "Importantly, the main limitation of this study is the low sample size of ROS1-, ALK- and RET-rearranged tumors, which is explained by the low prevalence of each tumor subtype." (PMID 39737401, 2024). "In addition, selpercatinib has already received an agnostic approval for all tumor types carrying RET fusion." (PMID 38612902, 2024).
tumor (continued). "Partly due to physiological adrenal uptake of 68Ga-DOTA-SSA PET/CT, more tumor specific 18F-FDOPA PET/CT may be preferred in PCCs that are small and/or related to known mutations in NF1, RET, VHL, or MAX." (PMID 38206185, 2024). "While sexual differences in chromatin organization and DNA repair might be plausible explanations for somatic PVs and somatic second hits in tumor suppressor genes, another mechanism must be at play for dominant germline PVs in, eg, RET." (PMID 38481600, 2024). "More recently, cabozantinib (1-N-[4-(6,7-dimethoxyquinolin-4-yl)oxyphenyl]-1-N’-(4-fluorophenyl)cyclopropane-1,1-dicarboxamide) has been tested in RET overexpressing cell cultures and PDXs from resected brain metastases, determining a reduction of RET phosphorylation and inhibiting tumor growth." (PMID 39211557, 2024). "Similarly, treatment with vandetanib reduced RET phosphorylation and activation, promoting tumor regression in BC patient-derived xenografts (PDXs)." (PMID 39211557, 2024). "For kinase-type PCCs, whether RET inhibitors can enhance the antigen presentation ability of tumor cells, and further provide chance for combination of kinase-targeted therapy and immunotherapy, needs to be verified by follow-up research." (PMID 38407266, 2024). "Encouragingly, SY-5007 demonstrated promising clinical activity, with significant anti-tumor efficacy observed in both treatment-naïve and previously treated patients across various RET-altered tumor types, including NSCLC, PTC, and MTC, irrespective of fusion partners and prior MKI exposure." (PMID 39489747, 2024). "Hence, selective RET inhibitors currently represent an agnostic therapeutic option for patients whose tumor harbor a RET fusion." (PMID 39211557, 2024). "RET variation is positively related to nodal metastasis in Chinese PTC, and anti-tumor immune response may play a role in nodal metastasis triggered by RET variation." (PMID 38734621, 2024). "These alterations cause RET activation in tumor cells, even in the absence of ligand-coreceptor GDFN interaction." (PMID 39199650, 2024). "Importantly, targeting RET with the multikinase inhibitor vandetanib potentiated the effect of tamoxifen, demonstrating a greater reduction in tumor growth compared to single-agent therapy." (PMID 39931212, 2024). "Clinical and preclinical studies indicated the efficacy and safety of multiple therapies for NSCLC patients with different aberrations, including EGFR exon 19 deletions or exon 21 (L858R) mutations, RET fusion-positive metastatic, ALK genomic tumor aberrations, EGFR exon 20 insertions." (PMID 37568193, 2023). "Selpercatinib and pralsetinib are selective RET inhibitors with significant improvement of outcome in patients with tumor harboring RET fusion; however, resistance mechanisms appear frequently, mainly driven by MAPK pathway bypass, secondary RET mutations, or in 5% via MET amplification." (PMID 37876974, 2023). "Our data suggest that vepafestinib would have broad activity against RET solvent front mutations as well as across various RET mutations and fusions, regardless of fusion partners, in a tumor-agnostic fashion." (PMID 37743366, 2023). "Given the frequent combination of RET inhibitors with immunotherapeutic agents in the management of other tumor types, these findings may have critical implications for RET as a therapeutic target in ER-negative tumor subtypes." (PMID 36918928, 2023). "The presence of RET mutation at both the germline or somatic level was more frequent in tumours with RET CNAs compared to those without (83.3% vs. 42.5%, p = 0.003)." (PMID 37835559, 2023). "Furthermore, it has been demonstrated that the tumor penetrance can be modulated by the genetic background of the RET transgenic mice." (PMID 37474617, 2023). "Both patients had confirmed tumor responses, including a dramatic decrease in intracranial disease for the second patient, thus providing proof-of-concept of the activity of selective RET inhibition." (PMID 37627175, 2023).